CXorf65 (chromosome X open reading frame 65)
Tractability: No criterion of Open Targets' tractability assessment is met for any kind of drug.
Gene: Protein-coding gene on chromosome X (71,103,889 to 71,106,788, reverse strand). Ensembl gene ENSG00000204165.
Gene Ontology:
Molecular function: RNA polymerase II cis-regulatory region sequence-specific DNA binding
Homologues: Orthologues: macaque CXHXorf65 (93% identical), dog CXorf65 (64% identical), pig CXorf65 (61% identical), rabbit CXorf65 (58% identical), guinea pig CXorf65 (57% identical), mouse Gm614 (56% identical), rat Cxhxorf65 (55% identical), zebrafish C14HXorf65 (31% identical).
Diseases named in the same sentence as CXorf65 in open-access papers:
CXorf65 is named in the same sentence as 2 diseases in open-access papers, as found by Europe PMC text mining. Sharing a sentence is not in itself a finding about the gene and the disease. The quoted sentences say what the papers report.
cancer (1 paper, 2021). A tumor composed of atypical neoplastic, often pleomorphic cells that invade other tissues. "Furthermore, three genes—Cxorf65, SSTR3, and ART3—had a testis-associated expression pattern and might represent novel Cancer/Testis antigens." (PMID 35145509, 2021).
CXorf65 also shares sentences with these, for which no sentence is quoted: Co-infection (1 paper).